LEPR (leptin receptor)
Diseases named in the same sentence as LEPR in open-access papers (continued):
Sharing a sentence is not in itself a finding about the gene and the disease.
Obesity (continued). "Selective disruption of BBS proteins causes obesity in mice and impairs the transport of the leptin receptor to the plasma membrane leading to leptin resistance in a manner independent of obesity." (PMID 26926121, 2016). "Similarly, the side effects that LEP and LEPR share with selective serotonin inhibitors such as “food craving”, “binge eating”, “hyperphagia” and “obesity” suggest a connection between serotonin signalling and leptin." (PMID 27673331, 2016). "To this aim, we treated lean, obesity-resistant, overweight and obese mice with one injection per week of the active pegylated leptin receptor antagonist peptide (PEG-LPrA2) or with vehicle (control untreated) during 4 weeks, and assessed tumor volume at euthanasia." (PMID 25599228, 2015). "To examine the potential role of the CDK8-CycC complex in obesity, insulin resistance and NAFLD, we first examined the protein expression profiles in both leptin receptor-deficient (db/db) and leptin-deficient (ob/ob) mice, two well-studied models of obesity with insulin resistance and fatty liver." (PMID 26042770, 2015). "In this study we found a gene-diet interaction for the 668 A/G polymorphism in the LEPR gene and 56 C/G in the APOA5 gene with a high intake of saturated fatty acids (SFA) and total fat was associated with obesity, hypercholesterolemia and hypertriglyceridemia." (PMID 26365669, 2015). "The soluble leptin receptor (sOB-R) that circulates in human plasma is capable of binding to leptin that could protect against obesity." (PMID 26180527, 2015). "To interrogate FGF21 pharmacology in a different species and confirm dependence on the leptin pathway on metabolic endpoints such as BW, glycemic control, we used Zucker fatty rats Strain 185 Crl:ZUC-Leprfa27 which lack the leptin receptor and develop obesity and hyperphagia." (PMID 26153793, 2015). "Our data confirmed the role of FTO, CTNNBL1, LEPR and PPARG in obesity predisposition." (PMID 24879436, 2014). "This study was to investigate the prevalence of single nucleotide polymorphisms (SNPs) in leptin gene LEP (A19G and G2548A) and leptin receptor gene LEPR (K109R and Q223R) and their association with fasting plasma leptin level (PLL) and obesity in a Malaysian suburban population in Kampar, Perak." (PMID 24947733, 2014). "We reasoned that impaired cytokine signaling through the leptin receptor might contribute to worsened lung injury in response to influenza A viral infection during obesity by reducing the rates of influenza A viral clearance." (PMID 25232724, 2014). "Leptin and leptin receptor (LEPR) genes have been suggested to be candidate genes for hypertension via their direct effects on regulation of blood pressure (BP) and adipose tissue metabolism, or indirect effect on obesity." (PMID 24522342, 2014). "The ZDF rat is an inbred rat model obtained through selective breeding (fa mutation) that results in shortened leptin receptor which does not effectively interact with leptin and is phenotypically expressed as obesity with high levels of leptin in the blood." (PMID 24468233, 2014). "In leptin-deficeint (Lepob/ob) and leptin-receptor-deficient (LepRdb/db) mice, the development of obesity increases HDL without an increase in VLDL, which has been shown to make these animals resistant to the development of atherosclerotic lesions." (PMID 24672716, 2014). "Abnormal LEPR, as well as abnormal leptin catabolism, has been detected in obesity development." (PMID 24051404, 2013). "Impaired hypothalamic regulation of energy balance is found in numerous genetic forms of human obesity, including congenital deficiency of leptin (MIM 164160), leptin receptor mutations (MIM 601007), MC4R melanocortin receptor mutations (MIM 601665), and Bardet-Biedl Syndrome (MIM 209900)." (PMID 23341784, 2013).
Obesity (continued). "The Q223R SNP (but not the K109R or K656N SNPs) of the LEPR gene has been reported to be associated with obesity and to predict a small percentage of body weight and body composition variability in a genetically homogeneous population." (PMID 24146750, 2013). "Furthermore, overexpression of the leptin receptor, which is related to obesity, is found in breast tumors with a high grade." (PMID 23181105, 2012). "Obesity may play the role of inducing lymphomagenesis by the co-effects of LEP 19 A>G, LEPR 233Q>R polymorphisms and immune dysfunction." (PMID 22666399, 2012). "Our search strategy is likely to have missed papers that included results on the association between the selected LEPR variants and obesity but have not mentioned LEPR in title or abstract." (PMID 22028824, 2011). "In the present study, we examined single nucleotide polymorphisms (SNPs) in the adiponectin, LEPR, MC4R and FTO genes in association with obesity in a cohort of young South African Asian Indian patients with acute myocardial infarction (AMI), with and without the metabolic syndrome." (PMID 21298202, 2011). "The finding of interaction between LEPR Gln223Arg genotypes and menopausal status and obesity may also partly explain the differences in reports from various populations." (PMID 19017403, 2008). "Zucker Fatty (ZF) rats with a leptin receptor defect exhibit obesity, insulin resistance with hyperinsulinemia and normal glycemia that progress to type 2 diabetes in 6–12 weeks; ZF rats have severe mitochondrial inhibition with low oxidation of palmitic acid to CO2." (PMID 18335029, 2008). "As circulating levels increase, leptin acts to modulate food intake, but in obesity, its rise with increasing body fat has limited effect on satiety, suggesting negative regulators of leptin and insulin signalling, such as leptin receptor and adiponectin, are present." (PMID 16160698, 2005). "To date, experimental approaches to the investigation of this novel link between obesity and immune function have been predominantly carried out in genetic models of obesity that either lack leptin (ob/ob mouse) or the long form of the leptin receptor (db/db mouse)." (PMID 15813957, 2005). "However, the increasing prevalence of obesity and T2DM, as well as their culmination in HFpEF, led us to use leptin receptor-deficient db/db mice as our preclinical model for this study, as these mice develop obesity by 4 weeks of age, T2DM by 12 weeks, and HFpEF by 24 weeks." (PMID 40723901, 2025). "In Chandigarh, India, next-generation sequencing in children with obesity identified one pathogenic variant in the MC4R gene, one likely pathogenic variant each in the LEPR, NTRK2, and LEP genes, as well as variants of uncertain significance in the POMC and LEPR genes." (PMID 40149731, 2025). "Consequently, zebrafish with leptin receptor deficiency exhibit dysregulated glucose homeostasis, rather than obesity, hyperphagia, and hyperlipidemia seen in mammals’ models like mice." (PMID 41108536, 2025). "Therefore, D‐mannose is effective in alleviating dietary obesity, but fails to control overweight in db/db mice, which surely have central deficiency of leptin receptor." (PMID 41163804, 2025). "Specifically, homozygous loss-of-function (LoF) mutations in genes such as LEP, LEPR, and homozygous and heterozygous in MC4R result in uncontrollable hyperphagia, an eating disorder characterized by excessive hunger and food intake, leading to extreme early-onset obesity." (PMID 39237720, 2025). "Setmelanotide has also been approved for the treatment of obesity and hunger due to genetic disorders such as Bardet-Biedl syndrome, pro-opiomelanocortin (POMC) loss-of-function, including proprotein convertase subtilisin/kexin type 1 (PCSK1), and LEPR deficiency." (PMID 40297673, 2025).
Obesity (continued). "Additionally, the GRGMLA haplotype might be a susceptibility factor for obesity, with significant associations between LEP and leptin receptor (LEP-R), LEP and ghrelin (GHRL), and GHRL and FTO." (PMID 39766314, 2024). "Three groups—no obesity (33 cases), obesity (26 cases), and overweight (41 cases)—were compared according to the family history of the 100 selected children, and we examined whether LEPR and LEP gene polymorphisms and 51 nt and 31 nt methylation were related." (PMID 39594868, 2024). "Moreover, altering leptin receptor endocytosis and intracellular transport is considered a possible approach to treating obesity (e.g., by fusing leptin with another molecule to improve its passage through the BBB, always confirming that this barrier is intact)." (PMID 38397015, 2024). "Accordingly, the finding that in obese leptin-deficient (ob/ob) and leptin receptor–deficient (db/db) mice plasma aldosterone levels are in normal range confirms the crucial role of leptin in sustaining increased aldosterone production in obesity." (PMID 38186879, 2024). "Given that LepR-Cre Slc7a5fl/fl mice showed impaired sympathetic tone and leptin insensitivity in LepR-expressing VMH neurons prior to the onset of obesity, we reasoned that LAT1 in LepR-expressing neurons may play an important role in regulating bone homeostasis in addition to energy homeostasis." (PMID 36862514, 2023). "Although we were not able to carry out direct evaluation of humoral and cellular immunity in our children with obesity, we found a high systemic oxidative stress level and a marked depletion of the antioxidant GSH in obese carriers with homozygous loss-of-function mutations in LEP or LEPR genes." (PMID 37659411, 2023). "Therefore, CD8+ T cells may retain their IFN-γ producing phenotype in the context of HFD-induced obesity, even when leptin receptor is deleted." (PMID 37276236, 2023). "The effect of obesity without leptin signaling was modeled by comparing female lean Zucker rats to pair fed obese Zucker rats, which possess mutant fa alleles of the leptin receptor gene." (PMID 37457883, 2023). "ObRb leptin receptor is subjected to inactivation in obese conditions as exemplified by the cleavage of its leptin-binding regions in the extracellular domain by matrix metalloprotease 2 which is secreted by astrocytes and AgRP neurons under the conditions of obesity." (PMID 37547309, 2023). "Although, LEP and LEPR follow an autosomal recessive mode of inheritance, there is a growing evidence that some variants in the heterozygous state in monogenic obesity genes such as LEP and LEPR could lead to severe childhood obesity, hyperphagia, and pituitary dysfunction." (PMID 37329217, 2023). "Genes encoding leptin (LEP), leptin receptor (LEPR), melanocortin 4 receptor (MC4R), proprotein convertase subtilisin/kexin type 1 (PCSK1), proopiomelanocortin (POMC), kinase suppressor of ras 2 (KSR2), adenylate cyclase 3 (ADCY3), and others contribute to the development and progression of obesity." (PMID 36141228, 2022). "Considering that the activation of LepR in hypothalamic neurons reduces food intake and may increase energy expenditure and fat oxidation, leptin sensitizing therapies will likely produce robust beneficial effects in the prevention and treatment of obesity." (PMID 35742928, 2022). "Several syndromic and monogenic disorders of obesity that have been identified include Prader–Willi syndrome, Bardet–Biedl syndrome, and loss-of-function mutations in the genes encoding for pro-opiomelanocortin (POMC), leptin, leptin receptor (LEPR) or the melanocortin-4 receptor (MC4R)." (PMID 35299971, 2022). "These analogs were tested in various mouse and rat models of obesity, glucose intolerance/insulin resistance and T2DM resulting from high-fat (HF) diet feeding (diet-induced obesity (DIO) models) or in rodents with nonfunctional leptin signaling due to a spontaneous mutation in the leptin receptor." (PMID 34867411, 2021).
Obesity (continued). "Nevertheless, the phenotypic heterogeneity of obesity caused by dysregulated LEPR may underestimate the contribution of other variants not completely known whose allelic frequencies change according to ethnic group." (PMID 34208585, 2021). "Moreover, gWAT Hand2 was significantly lower in mouse models of obesity, including HFD-induced obesity (referred to here as diet-induced obesity [DIO]) as well as genetically obese, leptin receptor-deficient db/db mice, and also inversely correlated with body weight." (PMID 34014371, 2021). "Given the correlation between leptin, obesity, insulin action and reproductive functions, we hypothesized that plasma leptin and sOB-R levels, and also LEP/LEPR variants might be associated with PCOS as well as infertility and recurrent pregnancy loss (RPL) in PCOS patients." (PMID 34407095, 2021). "On the other hand, diet-induced obesity is thought to arise from the development of central leptin resistance as a result of persistently elevated circulating leptin levels as well as from complex pro-inflammatory processes that directly interfere with hypothalamic leptin receptor signaling." (PMID 34064308, 2021). "Finally, an important positively selected gene (PSG) was found to be LEPR (leptin receptor) containing two positively selected sites which may lead to pseudogenization of this gene with possible significant effects on obesity and inflammation development." (PMID 34585119, 2021). "The implication that presence of LepR on cells of degenerated human IVD is directly related to negative effects of leptin—whose serum levels increase exponentially with an increasing volume of adipose tissue—likely oversimplifies the complex relationship between obesity, leptin pathway, and LDD." (PMID 33396484, 2020). "Finally we also investigated whether the effect of LEPR Q233R SNP genotype on obesity was influenced by urban/rural living." (PMID 31948470, 2020). "Leptin receptor gene (LEPR) polymorphism was related to obesity in women but not in men." (PMID 32998691, 2020). "Hence, some obesity-related genes (LEPR, NEGR1, TMEM18, and SH2B1) may play critical roles in preventing progression and metastasis of kidney cancer." (PMID 33299884, 2020). "Interestingly, some genes associated with obesity were also associated with AD by different genetic approaches: candidate gene approach FTO, by differentially expressed genes NRXN3, NPC1, NEGR1, or by GWAS approach: LEPR, BDNF, TNFα, and MTCH2." (PMID 32982666, 2020). "The increased LEPR expression observed in the Obese group suggests that the receptor plays a modulating role in the skin system control and that serum LEP may have a role in the pathogenesis of skin disease associated with obesity." (PMID 33316917, 2020). "The comparison of changes in the expression levels of obesity-related genes between the occurrence of cancer and patients' survival revealed four obesity-related genes (LEPR, NEGR1, TMEM18, and SH2B1), which might play critical roles in preventing the progression and metastasis of kidney cancer." (PMID 33299884, 2020). "Moreover, it has been found that a lower expression of the leptin receptor in the hippocampus and hypothalamus may have a significant impact on obesity and comorbid depression." (PMID 30991630, 2019). "Systemic low-grade inflammation may be a contributing factor for the lower levels of Tregs in obesity, however, it is interesting to note that leptin has been shown to induce proinflammatory cytokines and inhibit Tregs in leptin/leptin receptor – sufficient mice fed high-fat diet." (PMID 31191312, 2019). "Although knockout of the leptin receptor (lepr) gene failed to cause body obesity in zebrafish, a previous study showed that the adipostatic role of leptin in the regulation of β-cell number, insulin expression and glucose homeostasis remained conserved across vertebrates." (PMID 30718259, 2019).
Obesity (continued). "Regardless, the chronicity of obesity may suggest that any leptin regulation of adipocyte autopahgic process as we show here, even if with a small effect size due to LepR expression and/or to obesity-related leptin resistance, may nevertheless bear physiological relevance over time." (PMID 30676227, 2019). "Rare and pathogenic variations in the MC4R (MIM:155541), POMC (MIM:176830), LEP (MIM:164160), LEPR (MIM:601007) and few other genes of LEP‐melanocortin pathway have been found and very less frequency of mutations was accounted in different studies due to complexity in the pathogenesis of obesity." (PMID 31070016, 2019). "However, it has been reported that hematopoietic LEPR deficiency in mice did not change macrophage accumulation in WAT after diet-induced obesity versus wild-type mice." (PMID 29910742, 2018). "Although the role of LEP and LEPR gene polymorphisms and their involvement in various diseases have been investigated extensively throughout the world in different populations, the association of LEP and LEPR variants with obesity, BMI, and MetS is still controversial." (PMID 30583468, 2018). "Accordingly, leptin-deficient or LepR-deficient mice developed extreme obese phenotype without increased incidence of knee OA, suggesting that leptin signaling is essential to the development and progression of obesity-associated OA." (PMID 29910742, 2018). "Recent evidence suggests that the LEPR-b-STAT3 signaling pathway may be involved in FTO regulation by restricting energy in the hypothalamus and there is evidence that the leptin receptor (LEPR) variant rs1137101 is positively associated with obesity." (PMID 29679223, 2018). "Since no elevations in the expression levels of the leptin receptor or fat metabolism-associated genes were recorded in blastocysts recovered from obese female mice, the role of leptin in mediating the effects of obesity on embryos at the peripheral level is likely lower than expected." (PMID 28959235, 2017). "Deletion of the leptin receptor in these cells caused mild obesity, but this did not alter food intake, suggesting that leptin signaling per se may not mediate the effects we observed." (PMID 29262334, 2017). "Notably, ChrSd supplementation lowered the hepatic expression of genes previously reported to be candidate genes for obesity, such as Insig-1, lepR, neurotrophic tyrosine kinase receptor type 2 (Ntrk2), melanocortin 5 receptor (Mc5r), and matrix metallopeptidase 7 (Mmp7)." (PMID 27977712, 2016). "Thus, they underlined an association between the LEPR 223 gene polymorphisms in Mexican adolescents with hemodynamic and metabolic disorders secondary to obesity, but without being associated with the BMI of these children." (PMID 27015185, 2016). "Thus, acute LepR deletion leads to extreme obesity with moderate changes in glucose homeostasis." (PMID 27003683, 2016). "The detailed mechanisms of the interactions among these genes will be further studied to illuminate the relationship between LepR and reproduction, and between obesity and reproduction, especially in the ovary, which might help to clarify the mechanism of PCOS." (PMID 26529315, 2015). "Interestingly, inhibition of miR-200a could reverse obesity by increasing the level of the leptin receptor and insulin receptor 2 in the hypothalamus." (PMID 25629159, 2015). "Genes functioning in the leptin-melanocortin pathway such as those encoding leptin (LEP), leptin receptor (LEPR), melanocortin 4 receptor (MC4R), pro-opiomelanocortin (POMC) and brain-derived neurotrophic factor (BDNF) have been implicated in the monogenic form of obesity." (PMID 26363598, 2015). "Obesity is associated with hyperphagia, defective non-shivering thermogenesis, increased efficiency for food utilization, and preferential deposition of energy in adipose tissue, all triggered by leptin receptor abnormalities." (PMID 24809394, 2014).